IRS2 (insulin receptor substrate 2)
Diseases named in the same sentence as IRS2 in open-access papers (continued):
Sharing a sentence is not in itself a finding about the gene and the disease.
Atrophy (1 paper, 2025). Any weakening or degeneration, especially through lack of use. "For chronic stress-induced muscle atrophy and dysfunction, CTSS contributes to the loss of myotube myosin heavy chain content and the upregulation of Muscle RING-finger protein-1 (MuRF1) and Insulin Receptor Substrate 2 (IRS-2)." (PMID 40692794, 2025).
autistic disorder (1 paper, 2016). "Thus, relatively low activities of IGF pathway molecules such as IGF1, IRS1 and IRS2 may play a role as risk factors in the pathophysiology of autistic disorder/ASD, leading to the growth and development retardation." (PMID 27483248, 2016). "Replication studies are needed to determine the association between the IRS1 and autistic disorder/ASD, as well as the lack of association of IRS2, analyzing more polymorphisms in addition to rs1801123 and rs4773092." (PMID 27483248, 2016).
brain ischemia (1 paper, 2024). Diminished or absent blood supply to the brain caused by obstruction (thrombosis or embolism) of an artery resulting in neurologic damage. "But, in our experiments, there was no significant change in IRS-2 phosphorylation at Ser731 in the hippocampus or frontal cortex under the influence of intranasally administered insulin or inhibitors of autophagy and apoptosis in rats exposed to brain ischemia and reperfusion." (PMID 39057034, 2024).
breast adenocarcinoma (1 paper, 2008). "Transgenic mice for the IGF-I pathway, over-expressing IGF-I, IGF-IR, or IRS1 and IRS2 in the mammary gland, all develop breast adenocarcinomas." (PMID 18611244, 2008).
cervical cancer (1 paper, 2023). A primary or metastatic malignant neoplasm involving the cervix. "We study the participation of the insulin substrates IRS-1 and IRS-2 in the insulin signaling pathway in response to insulin and their involvement in the proliferation and migration of the cervical cancer cell line." (PMID 36975518, 2023). "The relationship between the expression levels of IRS-1 and IRS-2 and the activation of insulin signaling pathways has been poorly studied in cervical cancer cells." (PMID 36975518, 2023). "It has been reported that progesterone upregulates IRS-2 expression, altering the levels of IRS-1 and IRS-2 in HeLa cells expressing progesterone receptors; however, very little is known about the role of the insulin signaling pathway in cell proliferation and migration in cervical cancer." (PMID 36975518, 2023). "The objective of this study was to investigate which isoform of the insulin receptor is expressed in the HeLa cervical cancer cell line and to analyze the role of IRS-1 and IRS-2 in the signaling pathway of the insulin receptor and in regulating the proliferation and migration of HeLa cells (HPV+)." (PMID 36975518, 2023).
depression (1 paper, 2024). "There were five overlapping hub genes in the two datasets including CASP1, IRS2, PRKAR1A, SNAP23, and VTI1A, which were identified as the key genes in the comorbidity of PCOS and depression." (PMID 38674428, 2024). "However, little evidence has shown that IRS2 is a cause or an effect of depression until now." (PMID 38674428, 2024). "Thus, without convincing evidence from the literature and without SNP support, it is still open to discussion as to whether IRS2 can be considered as a key gene for the comorbidity of PCOS and depression." (PMID 38674428, 2024).
Dry skin (1 paper, 2023). Skin characterized by the lack of natural or normal moisture. "IRS2 is important for adequate wound healing, which is delayed in elderly skin and loss of EDA is associated with dry skin and eczema, which are more frequently observed in elderly people." (PMID 38500495, 2023).
ductal carcinoma in situ (1 paper, 2022). "IRS2 expression is low in ductal carcinoma in situ but increases significantly as tumor invasiveness increases." (PMID 35859293, 2022).
endometrioid adenocarcinoma (1 paper, 2022). An adenocarcinoma characterized by the presence of malignant glandular epithelial cells resembling endometrial cells. "However, in our CAFs model, despite an increased in IRS2 expression, there is a decreased in HAND2 expression, parallel to previously reported study which demonstrated loss of HAND2 expression in the stromal of atypical hyperplasia and endometrioid adenocarcinomas compared to normal fibroblasts." (PMID 35816477, 2022).
endometriosis (1 paper, 2024). The growth of functional endometrial tissue in anatomic sites outside the uterine body. "Interestingly, endometriosis-associated gene dysregulation in early secretory phase matches dysregulation in the transgenic mouse endometrium in the present study in terms of affected gene-set, above all the progesterone-regulated genes (e.g. Errfi1, Bcl6, Cited2, Irs2, Tgfb2, Gpx3, Tk1)." (PMID 38346980, 2024).
essential thrombocythemia (1 paper, 2016). A chronic myeloproliferative neoplasm that involves primarily the megakaryocytic lineage. "IRS2 expression was significantly higher in CD34+ cells from essential thrombocythemia patients compared to healthy donors, and in JAK2V617F MPN patients when compared to JAK2WT." (PMID 26755644, 2016).
familial dilated cardiomyopathies (1 paper, 2013). "Here we show that nexilin, a F-actin binding protein implicated in the pathogenesis of familial dilated cardiomyopathies, preferentially binds to IRS1 over IRS2 to influence glucose transport in skeletal muscle cells." (PMID 23383252, 2013).
focal segmental glomerulosclerosis (1 paper, 2016). A renal disorder characterized by sclerotic lesions in the glomeruli. "In another study, increased IRS2 mRNA was detected in DN patients compared to controls, while no significant changes IRS2 expression were present in biopsies from patients with focal-segmental glomerulosclerosis or membranous nephropathy." (PMID 26798653, 2016).
glucose metabolism (1 paper, 2022). "Here, we found that Kcnh6 attenuated glucose metabolism disorders by decreasing PEPCK and G6pase abundance and induced Glut2 and IRS2 expression." (PMID 36217412, 2022). "Our results indicated that KCNH6 expression attenuated glucose metabolism disorders by decreasing PEPCK and G6pase expression and inducing Glut2 and IRS2 expression." (PMID 36217412, 2022).
Huntington disease (1 paper, 2022). Huntington disease (HD) is a rare neurodegenerative disorder of the central nervous system characterized by unwanted choreatic movements, behavioral and psychiatric disturbances and dementia. "Increased IRS2 levels in a mouse model of Huntington’s disease significantly shortens lifespan and increases neuronal oxidative stress and mitochondrial dysfunction." (PMID 35859293, 2022).
hypercortisolemia (1 paper, 2022). "At the metabolic level, the observed increased availability of IRS2, IGFBP2 and, to a lower extent, IRS1 after treatment suggested an elevated sensitivity to insulin in VAT under hypercortisolemia." (PMID 35737302, 2022).
imbalance (1 paper, 2019). "Interestingly, many of the genes (such as sarcoplasmic reticulum Ca2 + -ATPases (SLN), Ras-related glycolysis inhibitor, and calcium channel regulator (Rrad), insulin receptor substrate 2 (irs2), and peptide transporter 2 (PEPT2)) are associated with metabolic imbalance and weight-related diseases." (PMID 31519904, 2019).
inflammatory bowel disease (1 paper, 2014). A spectrum of small and large bowel inflammatory diseases of unknown etiology. "It was also reported that IL-4 and IRS2 play a critical role in the regulation of immune responses and the pathogenesis of inflammatory bowel diseases." (PMID 25144185, 2014).
invasive lobular carcinoma (1 paper, 2022). "Of note, IRS2 mutations were recently associated with invasion in pleomorphic invasive lobular carcinoma." (PMID 35011716, 2022).
ischemia (1 paper, 2024). A hypoperfusion of the BLOOD through an organ or tissue caused by a PATHOLOGIC CONSTRICTION or obstruction of its BLOOD VESSELS, or an absence of BLOOD CIRCULATION. "In the forebrain regions, we studied the effect of ischemia and reperfusion, as well as the administration of insulin and autophagy and apoptosis inhibitors on the intensity of insulin receptor substrate-2 (IRS-2) phosphorylation at Ser731." (PMID 39057034, 2024).
ischemic cardiomyopathy (1 paper, 2026). Ischemic cardiomyopathy is a cardiomyopathy in which a weakness in the muscle of the heart due to inadequate oxygen delivery to the myocardium with coronary artery disease being the most common cause. "The hub genes, including STAT3, MDM2, LRP1, IRS2, PRKCD, CCND2, and CISH, were validated to be highly expressed in adipocytes in ischemic cardiomyopathy patients with end-stage heart failure." (PMID 41869532, 2026).
knee osteoarthritis (1 paper, 2025). "We employed a unilateral destabilization of the medial meniscus (DMM) to establish a murine knee osteoarthritis (OA) model and, through qPCR analysis, observed a significant decrease in IRS2 mRNA levels in the articular cartilage of DMM-induced OA knee joints." (PMID 41013182, 2025).
leukemia (1 paper, 2018). A malignant (clonal) hematologic disorder, involving hematopoietic stem cells and characterized by the presence of primitive or atypical myeloid or lymphoid cells in the bone marrow and the blood. "In the HEL JAK2V617F cell line, but not in U937 JAK2 wild-type leukemia cell lines, IRS2 was constitutively phosphorylated and associated with JAK2." (PMID 30328953, 2018).
lipodystrophy (1 paper, 2024). A congenital or acquired disorder characterized by abnormal loss or redistribution of the adipose tissue in the body. "Moreover, AT also partially reversed lipodystrophy-induced inhibition of insulin sensitivity-associated gene expression in both the livers (Irs2 and Akt2) and the skeletal muscles (Akt2) of Seipin/Apoe dKO mice." (PMID 38525541, 2024).
lymphoma (1 paper, 2017). A malignant (clonal) proliferation of B- lymphocytes or T- lymphocytes which involves the lymph nodes, bone marrow and/or extranodal sites. "Integrated ChIP-seq and mRNA microarray analyses identified Notch1/3 and Irs2 as direct transcriptional targets of Dlx5, a gene signature unique to lymphomas from Lck-Dlx5 mice as compared to T-cell lymphomas from Lck-MyrAkt2 mice, which were previously reported by our group." (PMID 28122332, 2017).
medulloblastoma (1 paper, 2025). A malignant, invasive embryonal neoplasm arising from the cerebellum. "Furthermore, the YAP/TEAD complex directly promotes the transcription of insulin receptor substrate 2 (IRS2), which subsequently activates phosphatidylinositol 3-kinase (PI3K)/AKT pathway in medulloblastoma." (PMID 40673277, 2025).
metastatic cancers (1 paper, 2014). A carcinoma which has spread from the original site of growth to another anatomic site. "Most metastatic cancers express higher levels of IRS-2 as compared to IRS-1." (PMID 24885964, 2014).
osteoarthritis (1 paper, 2025). A noninflammatory degenerative joint disease occurring chiefly in older persons, characterized by degeneration of the articular cartilage, hypertrophy of bone at the margins and changes in the synovial membrane. "This study provides valuable insights into the role of the IRS2/AKT/FOXO1 axis in osteoarthritis (OA), uncovering a mechanism by which FOXO1 is regulated through autophagy in chondrocytes, independent of acetylation." (PMID 41013182, 2025). "In this study, we focused on the role of IRS2 in chondrocytes and its involvement in osteoarthritis (OA)." (PMID 41013182, 2025). "In this study, we identified IRS2 as the most significantly downregulated molecule in osteoarthritis through bioinformatics analysis." (PMID 41013182, 2025). "Our findings suggest that exploring the role of IRS2 in osteoarthritis may provide valuable insights into its involvement in disease development and inform the design of therapeutic strategies." (PMID 41013182, 2025). "After histological staining of mouse knee joint sections, we further confirmed a significant reduction in IRS2 protein levels in DMM-induced osteoarthritis (OA), accompanied by an increase in matrix metalloproteinases 13 (MMP13) and a decrease in Aggrecan (ACAN)." (PMID 41013182, 2025).
Osteopenia (1 paper, 2017). Osteopenia is a term to define bone density that is not normal but also not as low as osteoporosis. "In rodents, including insulin receptor substrate-1 (IRS-1) and IRS-2 knock-out mice and streptozotocin-induced diabetic mice, studies have shown severe osteopenia, decreased bone formation, and severe growth retardation, respectively." (PMID 28630427, 2017).
ovarian tumor (1 paper, 2021). "The expression levels of ANGPTL4, PYGB and IRS2 were upregulated and those of ISG20 and SEH1L were downregulated in ovarian tumor tissues compared with normal tissues." (PMID 34229669, 2021). "Consistent with other studies, we observed that ANGPTL4, PYGB and IRS2 were highly expressed in ovarian tumor tissues and patients with high expression of ANGPTL4, PYGB or IRS2 had significantly lower OS rates than patients with low expression of these factors." (PMID 34229669, 2021).
overactive bladder (1 paper, 2024). Symptom of overactive detrusor muscle of the urinary bladder that contracts with abnormally high frequency and urgency. "Mice with conditional hepatic double-knockout of Irs1 and Irs2 show characteristics of T2DM and overactive bladder." (PMID 39292699, 2024).
periodontitis (1 paper, 2026). An acute or chronic inflammatory process that affects the tissues that surround and support the teeth. "T2DM+P and Periodontitis groups showed extensive inflammatory infiltrate in the gingival biopsies, with predominant IRS-2 immunopositive cells in the T2DM+P groups, independently of the metabolic control." (PMID 42072283, 2026). "In contrast, higher IRS2 mRNA levels were detected in individuals with Periodontitis at baseline, followed by a significant reduction over time." (PMID 42072283, 2026).
progressive neurodegenerative disorder (1 paper, 2023). "In research for HD, as well as a progressive neurodegenerative disorder, the researchers described that ZNF148 directly interacted with three known-HD genes (BCL2, CASP6, and IRS2)." (PMID 37360784, 2023).
prostate adenocarcinoma (1 paper, 2011). "In contrast with the large number of TICs found in this study, we found relatively few distant gene fusions, and experimentally verified only two novel ones in prostate adenocarcinoma: IRS2-NUFIP1 and SEC31A-C6orf62." (PMID 21261984, 2011).
rhabdomyolysis (1 paper, 2012). Necrosis or disintegration of skeletal muscle often followed by myoglobinuria. "We immunoprecipitated kidney tissue extracts from Dahl rats (high-salt diet, treated with either saline or nephrilin) and from CD1 mice (rhabdomyolysis model) using an anti-IRS2 antibody conjugated to agarose (see “Materials and methods”)." (PMID 22899279, 2012).
sarcopenia (1 paper, 2021). Progressive decline in muscle mass due to aging which results in decreased functional capacity of muscles. "High IRS2 mRNA levels in the older age group of these healthy and highly functional individuals is also consistent with the hypothesis that compromised insulin signaling plays a role in the development of sarcopenia and frailty." (PMID 33795677, 2021).
SHORT syndrome (1 paper, 2025). A rare disorder characterized by multiple congenital anomalies, including short stature, hyperextensibility of joints, ocular depression, Rieger anomaly and teething delay in which the cause of the disease is a mutation in PIK3R1 gene. "Attenuated insulin-induced association of p110α with Irs2 in the presence of activating p110 delta syndrome 2 (APDS2) and SHORT syndrome mutant p85α." (PMID 39835783, 2025). "Results of immunoblotting of anti-Irs2 immunoprecipitates from 3T3-L1 cells expressing wild-type, APDS2-associated, or SHORT syndrome-associated mutant p85α under the control of doxycycline (Dox) are shown." (PMID 39835783, 2025).
thyroid (1 paper, 2021). "This suggests that the relationship between miR-7-5p, IRS2 and EGFR may play a significant role in thyroid tumorigenesis." (PMID 34381564, 2021).
thyroid tumor (1 paper, 2021). A benign or malignant neoplasm affecting the thyroid gland. "MiR-7-5p, IRS2 and EGFR expressions are correlated with the aggressivity of thyroid tumors: more aggressive BRAFV600E positive PTC exhibit a more pronounced decrease of miR-7-5p expression and increase of IRS2 or EGFR expressions compared to BRAFV600E negative PTC." (PMID 34381564, 2021).
urothelial carcinoma (1 paper, 2022). A malignant neoplasm derived from the transitional epithelium of the urinary tract (urinary bladder, ureter, urethra, or renal pelvis). "Interestingly, targeted sequencing identified four mutations shared by all of the tissue samples, including the urothelial carcinoma: BRCA1 p.Val340GlyfsTer6, DICER1 p.Arg490His, IRS2 p.Arg744Cys, and PDGFRB p.Arg853Trp." (PMID 35260767, 2022).
virus infection (1 paper, 2016). "DEGs involving in virus infection were observed in the PPI network including CREB3L1, FDPS and IRS2, in which CREB3L1 was reported to be associated with iCell hepatocyte (induced pluripotent stem cell derived hepatocytes from Cellular Dynamics International) susceptibility to HBV infection." (PMID 26900848, 2016).
ZIKV infection (1 paper, 2020). "Interestingly, immune escape by ZIKV infection could be caused by downregulation of prolactin signaling including IRS2, PIK3C3, JAK3, STAT3, and IRF1 as well as mitochondria dysfunction and oxidative phosphorylation in myeloid dendritic cells." (PMID 32287277, 2020).